ATM (ATM serine/threonine kinase)
Diseases named in the same sentence as ATM in open-access papers (continued):
Sharing a sentence is not in itself a finding about the gene and the disease.
pancreatic cancer (continued). "DNA damage repair deficiency, for example, through BRCA1/BRCA2, ATM or PALB2 loss, is seen in ∼15% of all pancreatic tumours and may represent a window of opportunity for radiotherapy in these patients due to increased radiosensitivity as a result of genomic instability." (PMID 38979684, 2024). "Thus, phosphorylated ATM could be a possible target for pancreatic cancer treatment as well as a molecular marker to track patient prognosis." (PMID 37674118, 2023). "However, another study investigating pancreatic cancer cells revealed that the inhibition of WEE1/ATM could effectively down-regulate the expression of PD-L1 by blocking GSK-3β and reducing the expression of CMTM6." (PMID 36071479, 2022). "Based on the available literature, it is estimated that 17 to 25% of pancreatic cancer harbor somatic PVs in one of the genes involved in DDR, mainly those implicated in homologous recombination DNA damage response and repair (HR), such as BRCA1, BRCA2, ATM, PALB2, ATRX, and RAD51." (PMID 35563100, 2022). "Furthermore, in melanoma-prone families with pancreatic cancers, ATM variants were only observed in patients without germline CDKN2A mutations." (PMID 34573422, 2021). "MGPTs generally cover at least 10 common HR-related genes such as ATM, BARD1, BRCA1, BRCA2, BRIP1, CHEK2, NBS1 (NBN), PALB2, RAD51C, and RAD51D, all of whose germline alterations are associated with BRCAness phenotypes for predisposition to breast, ovarian, prostate, or pancreatic cancer." (PMID 35008774, 2021). "Further, retrospective studies suggest that pathogenic ATM mutations may be prognostic in pancreatic cancer, rather than predictive of therapeutic sensitivity." (PMID 34572943, 2021). "In a logistic regression model adjusted for age at diagnosis and family history of cancer, ATM and BRCA2 mutations were associated with personal history of breast or pancreatic cancer, whereas PALB2 mutations were associated with family history of breast or pancreatic cancer." (PMID 31497750, 2018). "Although chronic pancreatitis is an important risk factor for pancreatic cancer development most of the mutated genes found to contribute to pancreatic cancer susceptibility when defective are classic tumor suppressor genes, such as BRCA2, ATM, PALB2, p16, and STK11." (PMID 28881607, 2017). "Of the 6474 patients with pancreatic cancer, 27 (0.4%) had BRCA1 alterations, 108 (1.7%) had BRCA2 alterations, 76 (1.2%) had germline ATM alterations, 25 (0.4%) had PALB2 alterations, and 27 (0.4%) had CHEK2 alterations." (PMID 40361359, 2025). "Since then, additional genes involved in the HR-pathway, such as PALB2, ATM, and CHECK2, have been identified, and a clear link between HRD and breast, ovarian, prostate, and pancreatic cancer has been established." (PMID 40988318, 2025).
pancreatic cancer (continued). "Overall, this study highlights the potential for the first-in-class ATM inhibitor AZD1390 to enhance radiation-induced antitumoral immune responses and immunotherapy efficacy in pancreatic cancer." (PMID 38376927, 2024). "Co-inhibition of WEE1 combined with ATM reduced the expression of MMP-9, IL-8, CXCL1, CCL2, and CCL5, thus achieving an anti-migration effect in pancreatic cancer (PC)." (PMID 36071479, 2022). "To verify the state of expression of ALDOA, ATM and PLK1 in patient tissues, we randomly selected 78 patients diagnosed with pancreatic cancer in our centre." (PMID 34565365, 2021). "Both PLK1 and ATM regulate the cell cycle, and it is important to determine whether ALDOA, which connects ATM to PLK1, regulates the cell cycle arrest caused by DNA damage and whether this regulatory mechanism is significant in the development of pancreatic cancer." (PMID 34565365, 2021). "Proteins downstream of ATM, chiefly ATR and CHK1/2, are also potential targets for therapy in patients with pancreatic cancer." (PMID 31963441, 2020). "Deletion of ATM in mouse models of lung cancer and pancreatic cancer also induced sensitivity to PARP inhibitors and/or DNA damaging agents, as did inhibitors of the related protein kinase ATR (ATM and Rad3-related)." (PMID 32183301, 2020). "Except for these four driver genes, more and more genes are identified as the critical genes in the process of pancreatic cancer, including ret proto-oncogene (RET), AT-rich interaction domain 1A (ARID1A), and ATM." (PMID 31552163, 2019). "Our results further show that ZEB1-activated ATM/p-CHK1-mediated DNA repair contributed to gemcitabine resistance of pancreatic cancer cells." (PMID 31783584, 2019). "HS-173 significantly attenuated radiation-induced increases in the levels of p-AKT and p-ATM, indicating that HS-173 inhibited critical components of the DNA damage response in human Miapaca-2 and PANC-1 pancreatic cancer cells." (PMID 29348875, 2017). "To explore the mechanism by which VPA upregulates MICA and MICB in pancreatic cancer cells, we examined the expression and activation of components of the HER2/HER3, ATM/ATR, and PI3K/Akt pathways." (PMID 24885711, 2014). "A recently developed ATM inhibitor enhances radiation-induced T1IFN, leading to both innate and subsequent adaptive anti-tumoral immune responses and sensitization of immunotherapy-resistant pancreatic cancer." (PMID 38376927, 2024). "Three of them had not been detected by previous routine testing (ATM p.R1730* in GE21 pancreatic tumor, NRAS p.Q61K in GE15 melanoma, and BRAF p.V600E in GE01 undifferentiated embryonal sarcoma of the liver)." (PMID 38750555, 2024). "Taken together, we show that a clinical candidate ATM inhibitor enhances radiation-induced T1IFN, leading to both innate and subsequent adaptive antitumoral immune responses and sensitization of otherwise resistant pancreatic cancer to immunotherapy." (PMID 38376927, 2024).
pancreatic cancer (continued). "Germline pathogenic variants in ATM, such as the one identified in GE21, are known to increase the risk of pancreatic cancer, but germline testing for this gene is not routinely performed." (PMID 38750555, 2024). "Current National Institute for Health and Care Excellence guidelines for pancreatic cancer management do not include ATM, though it is included in other guidelines." (PMID 39209703, 2024). "In pancreatic cancer, BRD4770 induced senescent phenotype and activated the ATM (ataxia telangiectasia mutated) pathway to induce DNA damage without affecting ATR (ATM- and Rad3-related) pathway, which ultimately restrained the cell growth." (PMID 37306883, 2023). "The combination of ATM inhibition and radiotherapy was further shown to increase PDL-1 expression and tumor sensitivity to anti-PDL-1 therapy in a mouse model of pancreatic cancer, accompanied by an increased tumoral infiltration of CD8+ T cells that established immunological memory." (PMID 37627155, 2023). "Several radiosensitizers have been clinically studied in a variety of malignancies, including CHK1/CHK2 inhibitors, ATM/ATR inhibitors, and PARP inhibitors, but clinical trials of pancreatic cancer-related radiosensitizers are still relatively scarce and most are in the preclinical stage." (PMID 35053488, 2022). "For example, the DDR genes BRCA1, BRCA2 and ATM, or PALB2, each one usually found mutated in no more than 3.5% of cases, increase pancreatic cancer risk when altered at the germline level." (PMID 35563100, 2022). "ATM serine/threonine kinase (ATM), stratifin (SFN), and growth arrest and DNA damage 45 alpha (GADD45A), which would be activated and arrest cell cycle in response to DNA damage, were up-regulated in pancreatic cancer cells after anlotinib treatment." (PMID 33748143, 2021). "For example, although pre-clinical studies suggest the sensitivity of ATM mutant pancreatic cancer to PARPi this has not been seen clinically." (PMID 34572943, 2021). "Similarly, a study by Smith and colleagues using gene sequencing assessed ATM in two series of patients: a French-Canadian series of 114 patients with PDAC and a Quebec pancreas cancer study series of 236 patients with PDAC." (PMID 31963441, 2020). "Together, these data demonstrate that DNA-damage responses downstream of ATM are functional in KC and KCATMΔ+ pancreatic tumors, and absent in KCATMΔΔ pancreatic tumors." (PMID 28894253, 2017). "Consequently, the combination treatment showed a significant reduction in phosphorylation of KAP1 and 53BP1, a marker for DSB repair, implying that inhibition of ATM and DNA-PKcs is sufficient to inhibit downstream signaling through KAP-1 in pancreatic tumors." (PMID 29348875, 2017). "Immunostaining results also showed scattered cells expressing the ATM target phospho-Kap16, 7 in both the KC and KCATMΔ+ pancreatic tumor epithelium, and absence of this protein in KCATMΔΔ pancreatic tumor epithelial cells." (PMID 28894253, 2017). "Together, these results are consistent with the notion that defects in signaling by the ATM pathway, which involves the human homolog of TEL1, may play important roles in the formation of the GCRs seen in a fraction of metastatic pancreatic cancer." (PMID 24699249, 2014). "Interestingly, PRRX1 could transcriptionally maintain the expressions of DDR genes including ATM, ATR, BRCA1, PRKDC, and XRCC1, in PANC1 pancreatic cancer cells." (PMID 40114375, 2025). "A pancreatic cancer case had insufficient tissue for TGP, so the ATM variant could not be confirmed on the somatic sample." (PMID 41465149, 2025).
pancreatic cancer (continued). "Hence, pancreatic tumor cells expressing high levels of TOPBP1 may exhibit heightened sensitivity to olaparib, leading to an exacerbation of the ATM pathway burden." (PMID 39920847, 2025). "We found that enhanced T1IFN expression by ATM inhibitor in combination with radiation was mediated by the POLIII/RIG-I/MAVS signaling pathway, independent of the canonical cGAS/STING pathway, suggesting the potential dysregulation of cGAS/STING signaling in pancreatic cancer." (PMID 38376927, 2024). "In another study with pancreatic cancer cells treated with gemcitabine in combination with ATR inhibitor ceralasertib (AZD6738), pharmacologic inhibition with the ATM inhibitor AZD0156 or knockout through CRISP-R of ATM led to replication catastrophe and cell death." (PMID 36975505, 2023). "Genetic alterations in tumor suppressor genes found in lower frequency (<10%) in pancreatic cancer include STK11/LKB1, MKK4, TGFβ R1 (ALK 5, chromosome 9q), TGFβ R2 (chromosome 3p), ACVR1β (ALK 4, chromosome 12q), ACVR2 (chromosome 2q), FBXW7 (CDC4), EP300, BRCA2, ATM, and AKT2." (PMID 24624093, 2014). "Although the other variants in BRCA1, ATM, and POLQ were not previously reported and were identified as novel variants in this current study, pathogenic variants in these genes have also been reported in pancreatic cancer and therefore these genes have been known to cause PDAC." (PMID 37234870, 2023). "In line with this, although ATM and CHEK2 mutations have been suggested to associate with increased response to DNA-damaging therapy, a recent analysis showed that ATM and CHEK2 mutant pancreatic cancer does not show evidence of HRD by multiple genetic HR classifiers." (PMID 34572943, 2021). "For example, we did not include females with multiple PVs, and females with ATM or BRCA2 PVs who later developed pancreatic cancer, despite progress in earlier detection of pancreatic cancer." (PMID 36856935, 2023). "A recently published study combining two parallel phase 2 clinical trials assessed olaparib monotherapy in 24 patients with previously treated pancreatic cancer and non-BRCA HR gene alterations (somatic BRCA, germline or somatic ATM, PALB2, ARID1A, PTEN, RAD51, CCNE and FANCB)." (PMID 34572943, 2021).
lung carcinoma (201 papers, 2008 to 2025). "The observed suppression of ATM expression in CPS1-overexpressing lung carcinoma cells creates a compounded DNA repair deficiency phenotype, mechanistically explaining the enhanced radiation sensitivity." (PMID 40565327, 2025). "Significant associations with lung cancer and polymorphisms in genes involved in DNA damage sensing (ATM) and, in four genes encoding proteins involved in mismatch repair (LIG1, LIG3,MLH1, and MSH6) found." (PMID 40958859, 2025). "ATM mutations have been identified in several cancer types, including ovarian, prostate, and lung carcinomas." (PMID 40584698, 2025). "Ataxia telangiectasia mutated (ATM) mutations represent the most common homologous recombination deficiency (HRD) mutation in non‐small cell lung cancer (NSCLC)." (PMID 40622001, 2025). "ATM is frequently mutated in human cancers, and approximately 3% of lung cancers have biallelic mutations in ATM, i.e., including 3.5% of lung adenocarcinomas (LUAD) and 1.4% of lung squamous cell carcinomas (LUSC)." (PMID 38807759, 2024). "Approximately 3% of lung cancers harbor mutations in the ATM gene, i.e., 3.5% of adenocarcinomas and 1.4% of squamous cell carcinomas." (PMID 38807759, 2024). "Meanwhile, patients with biliary tract, uterine, small bowel & ampullary, as well as lung carcinomas who tested positive for a hereditary cancer susceptibility syndrome had a germline ATM pathogenic variant in 9% - 12.7% of cases." (PMID 36865800, 2023). "The mutation frequency of ATM is highest in mantle cell lymphoma at 40% followed by colorectal cancer at 20% and prostate and lung cancer at 10%." (PMID 37627223, 2023). "It has been shown that ATM loss is synthetic lethal with DNA-PK and more than 20% of non–small cell lung cancer (NSCLC) cell lines are ATM deficient." (PMID 37663435, 2023). "We interrogated its in vitro activity in ATM-deficient lung cancer models and demonstrated its synergistic antiproliferative activity with different classes of compounds used in cancer treatment." (PMID 37663435, 2023). "At least in cellulo and ex vivo we show that low concentration of ATM inhibitor is able to synergise with IR to treat PTEN-deficient tumors in genetically well-defined IR resistant lung cancer models." (PMID 35477555, 2022). "This is important as ATM heterozygous mutation is frequently found in human cancer and in lung carcinomas in particular." (PMID 35628590, 2022). "Germline heterozygous variants of ATM have been associated with lung cancer susceptibility and onset." (PMID 35628590, 2022). "For example, knock-down TUBA1C by shRNA in lung cancer cells with ATM mutation showed a worse survival than cells with wild-type ATM (P = 0.01, one-sided Wilcoxon rank-sum test)." (PMID 36180906, 2022). "In recent years, many studies have reported that ATM mutations are involved in the development of lung cancer." (PMID 36243681, 2022). "Ataxia Telangiectasia Mutated (ATM) upregulated PD-L1 expression through activated JAK/STAT3 signaling pathway in lung cancer with cisplatin resistance." (PMID 34088360, 2021). "MiR-18-5p was reported to be a potential target for improving radiosensitivity in lung cancer by regulating the ataxia telangiectasia mutated (ATM) gene and hypoxia-inducible factor 1 alpha (HIF-1α) gene." (PMID 34572367, 2021). "Previous case-control studies in Caucasian and Han Chinese populations have shown that several ATM gene polymorphisms are associated with increased risk of lung cancer." (PMID 32329754, 2020).